NUP98 (nucleoporin 98 and 96 precursor)
Diseases named in the same sentence as NUP98 in open-access papers (continued):
Sharing a sentence is not in itself a finding about the gene and the disease.
Alzheimer disease (4 papers, 2021 to 2025). A progressive, neurodegenerative disease characterized by loss of function and death of nerve cells in several areas of the brain leading to loss of cognitive function such as memory and language. "This is further supported by in vitro experiments, which showed that NUP98 triggers tau aggregation and accelerates tau fibrilization seen in Alzheimer’s disease and tauopathy brains." (PMID 34019093, 2021). "Using co-immunoprecipitation from human Alzheimer’s disease brain tissue, these studies demonstrated direct binding between tau and NUP98 and that tau interacts with nuclear pore proteins enriched in phenylalanine-glycine (FG) repeat domains." (PMID 34019093, 2021). "In another example, we looked at Nup98, the large nucleoporin protein that is involved in transport across the nuclear pore complex but is found phase-separated in certain cancers and deposited in amyloid fibrils in Alzheimer’s disease where tau is also present." (PMID 40853992, 2025).
HIV-1 infection (4 papers, 2013 to 2024). The type species of lentivirus and the etiologic agent of acquired immunodeficiency syndrome (AIDS). "We aimed to further understand the multifaceted function of NUP98 in HIV-1 infection and decipher the underlying mechanism driven by NUP98 that regulates HIV-1 propagation." (PMID 38449868, 2024). "To further understand how the levels of the NUP98 protein were downregulated by HIV-1 infection, we checked the total mRNA that encodes NUP98 in infected SupT1 and HEK293T cells." (PMID 38449868, 2024). "We observed a decrease in the levels of the NUP98 protein during HIV-1 infection in both SupT1 and HEK293T cell lines." (PMID 38449868, 2024). "Downregulation of NUP98 in a host cell upon HIV-1 infection supports the concept of evolutionary conflicts between viruses and host antiviral factors." (PMID 38449868, 2024). "Here, we investigated the regulatory role of NUP98 on HIV-1 as we observed a lowering of its endogenous levels upon HIV-1 infection in CD4+ T cells." (PMID 38449868, 2024). "Overall, we infer that NUP98, which was downregulated upon HIV-1 infection, functions as a negative regulator of HIV-1 LTR-driven transcription, consequently lowering released virions." (PMID 38449868, 2024). "NUP358, NUP214, NUP98 and NUPL2 have been described as cytoplasmic filament nucleoporins and have all been previously implicated in HIV-1 infection." (PMID 30496303, 2018). "While the effects of NUP98 depletion on HIV-1 infection are relatively modest, this protein can also co-sediment with HIV-1 CA-NC tubes in vitro." (PMID 24130490, 2013). "We observed that the percentage of infection by HIV-1 was nearly 50% lower in HEK293T cells as compared with SupT1 cells, which indicated that the moderate lowering in NUP98 protein levels upon HIV-1 infection in HEK293T cells was probably due to low infection in this cell type." (PMID 38449868, 2024). "Notably, knock-down of NUP214, NUP62 or NUP98 had minimal effects (<2-fold) on HIV-1 infection in control cells, indicating that each of these nucleoporins promote MX2 anti-viral function." (PMID 30496303, 2018). "In comparison to uninfected cells, we did not observe any significant change in the total NUP98 mRNA upon infection in both cell types, suggesting that HIV-1 infection is not affecting either the transcription or stability of NUP98 encoding mRNA in these conditions." (PMID 38449868, 2024). "In this study, we examined the expression levels of NUPs, each representing a subcomplex in NPC, during the late stages of HIV-1 infection and demonstrated a non-canonical antiviral role of NUP98 in HIV-1 infection." (PMID 38449868, 2024). "Moreover, some Nup depletions (SEH1, NUP85, NUP160, SEC13, NUP98, NUP107, ELYS/ACHTF1, NUP93, NUP205, NUP88, and NUP214) that reduced both HIV-1 infection and MX2 activity in dividing HeLa cells, affected MX2 activity but not HIV-1 infection in non-dividing HeLa cells." (PMID 30084827, 2018).
myeloproliferative disease (3 papers, 2012 to 2024). "In that study, some NUP98-HOXD13 mice developed myeloproliferative disease at the 4-week post-transplant mark but none progressed to AML (except those engineered to concurrently express the TALE homeobox gene Meis1, a strong mediator of NUP98-associated leukemia during a 6-month study period." (PMID 38396286, 2024).
prostate carcinoma (3 papers, 2022 to 2025). A carcinoma that arises from epithelial cells of the prostate gland. "Studies have stated that the MAPK pathway plays a significant role in photoaging, and it has also been found that the knockdown of NUP98 in PC3 prostate cancer cells upregulates the level of c‐Jun N‐terminal kinase (JNK) phosphorylation and activates the MAPK pathway." (PMID 40097984, 2025).
cardiovirus infection (2 papers, 2019 to 2022). "Most importantly, FG-NUPs that had previously been shown to be hyperphosphorylated during cardiovirus infection: NUP62, NUP98, NUP153 and NUP214 exhibited statistical significance." (PMID 36508477, 2022). "For example, enterovirus and cardiovirus infections alter NPC composition to relocalize some nuclear proteins to the cytoplasm, whereas enteroviruses are known to induce degradation of nucleoporins Nup62, Nup98, and Nup153." (PMID 31875556, 2019).
Myelodysplasia (2 papers, 2010 to 2023). Clonal hematopoietic stem cell disorders characterized by dysplasia (ineffective production) in one or more hematopoietic cell lineages, leading to anemia and cytopenia. "Aside from the variable pathogenetic roles of different NUP98-fusions, NUP98-rearranged murine models show a huge variability in phenotypes such as myeloproliferation, myelodysplasia, and secondary or de novo leukemic transformation." (PMID 37296904, 2023). "It is interesting to note that NUP98 and MLL gene rearrangements are associated with myelodysplasia, a condition that is often associated with erythroid hyperplasia and abnormal erythroid maturation." (PMID 20805992, 2010).
myeloid malignancies (2 papers, 2015 to 2021). "KMT2A fusions were the most common (n = 28, 60%, GRIN p = 1.86 × 10−74) and other in-frame fusions previously reported in myeloid malignancies involving NUP98 (n = 3) and ETV6 (n = 2) were also observed." (PMID 33579957, 2021).
neuroblastoma (2 papers, 2012 to 2026). Neuroblastoma (NB) is the most common solid, extracranial childhood tumor. "Instead, higher levels of NUP62, NUP93, and NUP98 were correlated with mortality, high-risk, advanced stages of International Neuroblastoma Staging System (INSS), or disease progression in 498 NB patients (GSE62564), and associated with worse survival outcome." (PMID 41510169, 2026).
T-cell leukemia (2 papers, 2020 to 2024). A malignant disease of the T-lymphocytes in the bone marrow, thymus, and/or blood. "Since CCDC28A also fuses with NUP98 to form the NUP98::CCDC28A fusion gene in T-cell leukemia, it is likely that the oncogenic activity of CCDC28A enhances the leukemic activity of NPM1::CCDC28A." (PMID 39443736, 2024).
triple-negative breast carcinoma (2 papers, 2019 to 2024). An invasive breast carcinoma which is negative for expression of estrogen receptor (ER), progesterone receptor (PR), and human epidermal growth factor receptor 2 (HER2). "In patients with triple-negative breast cancer, high expression levels of NUP98, identified by immunohistochemistry, have been proposed to be a predictor of response to anthracycline-based chemotherapy and poor overall survival." (PMID 39196408, 2024).
viral myocarditis (2 papers, 2016 to 2019). Myocarditis that is caused by an infection with a viral agent. "To understand the molecular pathogenesis of CVB3 infection and provide strategies for developing treatments, we examined the role of a key nuclear pore protein 98 (NUP98) in the setting of viral myocarditis." (PMID 31396490, 2019). "In the present study, we sought to understand the role of NUP98 in the pathogenesis of viral myocarditis and its impact on the hypothetically cardioprotective NRG1-ERBB4/PSEN1 signaling axis." (PMID 31396490, 2019). "Employing a well-established murine model of viral myocarditis, we showed that Nup98, Nrg1, and erbB4 are all upregulated in the myocardium during the acute phase (7 dpi)." (PMID 31396490, 2019).
amyotrophic lateral sclerosis (1 paper, 2025). Amyotrophic lateral sclerosis (ALS) is a neurodegenerative disease characterized by progressive muscular paralysis reflecting degeneration of motor neurons in the primary motor cortex, corticospinal tracts, brainstem and spinal cord. "In amyotrophic lateral sclerosis (ALS) and FTD, the misassemblage of nucleoporins, including NUP98 and NUP153, is observed." (PMID 40868276, 2025).
cataract (1 paper, 2023). Partial or complete opacity of the crystalline lens of one or both eyes that decreases visual acuity and eventually results in blindness. "The NUP98-mutated siblings share bilateral cataracts and early onset of aging-associated diseases with the Werner prototypic aging syndrome (WS)." (PMID 36835439, 2023).
ciliopathies (1 paper, 2023). "Nek2 expression in Xenopus LRO and kidneys links it to ciliopathies, with Nup98 interaction affecting cilium resorption." (PMID 37908226, 2023). "Despite an accumulation of evidence highlighting the roles of NUP62 and NUP98 in cilia, there are as yet no direct indications from human diseases or model organisms to establish a clear link between NUP62/98 and ciliopathies." (PMID 37908226, 2023).
Coagulopathy (1 paper, 2022). "Coagulopathy was reported in GTF2I-RARA, FNDC3B-RARA, NUP98-RARA, and TNRC18-RARA-positive AML." (PMID 35494081, 2022).
colorectal adenocarcinoma (1 paper, 2025). The most common type of colorectal carcinoma. "It was found that elevated expression of RPL31, CCT2, RPL17, and NUP85, as well as downregulation of NUP98, CDC37, DNM2, and SNRPN resulted from corresponding μ-ASOs treatment, correlating with improved survival in colorectal adenocarcinoma patients according to the TCGA database." (PMID 41373892, 2025).
hepatic cancer (1 paper, 2019). "More recently, a study has revealed novel role for NUP98 as a potential tumour suppressor in hepatic cancer." (PMID 30935371, 2019).
hepatocellular carcinoma (1 paper, 2016). A malignant tumor that arises from hepatocytes.
invasive breast carcinoma (1 paper, 2019). A carcinoma that infiltrates the breast parenchyma. "Furthermore, given the significant expression of NUP98 in both DCIS and invasive breast cancer relative to normal breast provides further utility for this biomarker in the early diagnosis of the disease." (PMID 30935371, 2019).
Larsen syndrome (1 paper, 2026). A rare skeletal dysplasia characterized by congenital dislocation of large joints, foot deformities, cervical spine dysplasia, scoliosis, spatula-shaped distal phalanges and distinctive craniofacial abnormalities, including cleft palate. "Additionally, this study identified a novel fusion form, NUP98-GALNTL4, which encodes galactosyltransferase-I, a product of GALNTL4, that has been associated with Ehlers–Danlos syndrome and Larsen syndrome on Reunion Island through genetic mutations." (PMID 41446535, 2026).
lymphoid leukemia (1 paper, 2024). A malignant lymphocytic neoplasm of B-cell or T-cell lineage involving primarily the bone marrow and the peripheral blood. "NUP98–and to a lesser extent, NUP214–have been found to be part of various fusion events involved in the development of several different myeloid and lymphoid leukemias." (PMID 38562379, 2024).
Miscarriage (1 paper, 2017). A pregnancy that ends at a stage in which the fetus is incapable of surviving on its own, defined as the spontaneous loss of a fetus before the 22th week of pregnancy. "NUP98, on the other hand, is a novel gene implicated in miscarriages." (PMID 28345611, 2017).
monocytopenia (1 paper, 2026). "Moreover, in the Nup98-Hoxd13 model, the neutropenia and monocytopenia in Fbxo11-knockdown animals were even worse and were accompanied by striking BM hypercellularity and a reduction in NPM1 protein levels." (PMID 41542766, 2026).
myocarditis (1 paper, 2019). Myocarditis is a condition that is characterized by inflammation of the heart muscle (myocardium). "Tissue was lysed for western blot analysis of Nup98 cleavage and its target gene expression, or formalin fixed/paraffin embedded and stained by immunohistochemistry for gene expression and myocarditis." (PMID 31396490, 2019). "Taken together, this study demonstrated that NUP98, an important regulator of antiviral gene transcription, is targeted by coxsackievirus protease 2A early on in the model of CVB3 myocarditis." (PMID 31396490, 2019). "Collectively, CVB3-induced cleavage of NUP98 and subsequent impairment of the cardioprotective NRG1-ERBB4/PSEN1 signaling cascade may contribute to increased myocardial damage in the context of CVB3-induced myocarditis." (PMID 31396490, 2019).
neutropenia (1 paper, 2026). A decrease in the number of neutrophils found in the blood. "Using in vivo murine MDS models driven by RUNX1- or Nup98-Hoxd13, we found that animals with knockdown of Fbox11 had exacerbated neutropenia compared with animals with intact Fbxo11." (PMID 41542766, 2026).
ovarian carcinoma (1 paper, 2023). A malignant neoplasm originating from the surface ovarian epithelium. "In ovarian cancer, JADE2 has been shown to be highly overexpressed and may function to regulate YAP1 a critical ovarian cancer oncogene, whilst a gene fusion between JADE2 and NUP98 has been observed in a pediatric acute myeloid leukemia." (PMID 37761019, 2023).
Pancytopenia (1 paper, 2012). An abnormal reduction in numbers of all blood cell types (red blood cells, white blood cells, and platelets). "Furthermore, mice with AML induced by co-expression of BCR/ABL and the Nup98/HoxA9 fusion protein showed a loss of osteolineage cells in the marrow, which may have contributed to the underlying pancytopenia." (PMID 22952867, 2012).
poliovirus infection (1 paper, 2021). An disease or disorder caused by infection with Enterovirus C. "Later, it was shown that another FG-nucleoporin, NUP98, was also degraded during poliovirus infection, but at an earlier time of infection (around 2 h.p.i compared to 4 h.p.i for NUP153 and NUP62)." (PMID 34201715, 2021).
spina bifida aperta (1 paper, 2020). "Within our two cases of thoracic spina bifida aperta-only, one case carried two PDRVs in genes involved in nuclear pore complex function (NUP98:NM_139132:c.4837C > T: p.R1613C and c.5026C > A: p.H1676N)." (PMID 32650820, 2020).
tauopathy (1 paper, 2024). Neurodegenerative disorders involving deposition of abnormal tau protein isoforms (tau proteins) in neurons and glial cells in the brain. "Impaired nuclear transport has also been observed in cells positive for phosphorylated tau in AD brain, as well as in cell and mouse models of tauopathy, and the C-terminus of tau interacts with the nucleoporin, Nup98, in vitro." (PMID 39009859, 2024).
thyroid cancer (1 paper, 2021). "Although little is known about NUP98 mutation in thyroid cancer, it is known that it mediates selective transport of RNA molecules between the cytoplasm and nucleus and also regulates cell cycle progression through interactions with several cofactors." (PMID 34680332, 2021). "NUP98 variants have not been previously reported in thyroid cancer." (PMID 34680332, 2021).
Werner syndrome (1 paper, 2024). "The progeroid signs shared by NUP98-mutated sibs and RTS1/RTS2 individuals are also the hallmarks of Werner syndrome, which is characterized by accelerated aging, along with an increased incidence and early onset of sarcomas." (PMID 39273335, 2024).
ZIKV infection (1 paper, 2020). "We found that while during DENV infection the integrity and distribution of at least three nucleoporins (Nup), Nup153, Nup98, and Nup62 were altered, during ZIKV infection, the integrity of TPR, Nup153, and Nup98 were modified." (PMID 32466480, 2020). "Our results indicate that during DENV infection, the integrity and distribution of at least Nup153, Nup98, and Nup62 were disrupted, while during ZIKV infection, the integrity of TPR, Nup153, and Nup98 were altered." (PMID 32466480, 2020). "In concordance with this result, a significant reduction in Nup98 levels of 81% and 97% was observed at 24 and 48 post-ZIKV infections, respectively." (PMID 32466480, 2020).